TNF (tumor necrosis factor)
Diseases named in the same sentence as TNF in open-access papers (continued):
Sharing a sentence is not in itself a finding about the gene and the disease.
atherosclerosis (continued). "However, treatment with etanercept, a TNF-α inhibitor, improved arthritis and atherosclerosis without affecting lipid concentrations, suggesting a noncausal relationship between dyslipidemia and atherosclerosis." (PMID 24453423, 2013). "Therefore, the absence of increased circulating TNF-α levels in our study may help to explain why atherosclerosis development was only mildly increased." (PMID 24303000, 2013). "In mice with diet-induced atherosclerosis treatment with a RANTES chemokine antagonist, hereby blocking CCR5, reduced atherosclerotic plaque formation, associated with reduced proliferation and secretion of Th1 cytokines IFN-γ and TNF-α, without difference in Th2 cytokine profile." (PMID 22348061, 2012). "Our results indicate that patients treated with TNFα inhibitors, but not other biological therapies, have the smallest CIMT, and hence, a lower rate of subclinical atherosclerosis." (PMID 35054229, 2021). "Moreover, the decreased risk of cardiovascular disease in RA patients who were treated with TNF blockers and methotrexate further supports the hypothesis that accelerated atherosclerosis in RA is primarily triggered by chronic inflammation, not by traditional cardiovascular risk factors." (PMID 31174287, 2019). "In addition, the serum TNF-α and IL-1β levels were increased in atherosclerosis rabbits, and kaempferol groups showed lower TNF-α and IL-1β levels, indicating that the down-regulation of E-sel, ICAM-1, VCAM-1 and MCP-1 might be mediated by the reducing of TNF-α and IL-1β." (PMID 23895132, 2013). "Psoriasis vulgaris patients with atherosclerosis had higher levels of hs-CRP (median = 1.22; interquartile range—IQR = 0.34–12.11) and IL-17A (median = 1.30; IQR = 0.43–4.28), but a lower level of TNF-α (median = 0.54; IQR = 0.13–3.41) compared to those without atherosclerosis (p < 0.05)." (PMID 39104857, 2024). "In contrast, TNF, interferon regulatory factor 2 (IRF2) and interferon gamma (IFNG) were predicted to be inhibited and insulin activated in both datasets, and the computing of LARP1 activity was not possible in VAT samples from humans with atherosclerosis." (PMID 35737302, 2022). "However, deletion of hematopoietic CARD9 shows no protective effects on atherosclerosis, probably because of no significant reduction of cytokines secretion (IL-6 and TNF-α) or mRNA expressions (IL-1β, IL-10, TNF-α, and MCP-1)." (PMID 35432375, 2022). "In contrast, salusin-α could selectively down-regulate the levels of IL-6 and TNF-α in plasma not MCP-1 and VCAM-1 in the aorta, suggesting little effects of salusin-α on inflammation in atherosclerosis progression." (PMID 24621517, 2014). "The fact that we used controls matched for atherosclerosis, and that elevated serum sTNF-RI and sTNF-RII concentrations are increased in carotid atherosclerosis may explain why our data are not as clearly differentiated in respect of TNF-α as those where healthy controls were used." (PMID 17328808, 2007).
depression (1,923 papers, 2006 to 2026). "In another study of clinically depressed adolescents, TNF-α was associated with parent-reported depression severity." (PMID 41515266, 2026). "Interleukin‐6 (IL‐6), tumor necrosis factor‐alpha (TNFα), and interleukin‐1 beta (IL‐1β) are three significant cytokines that have been widely investigated concerning the causes of major depressive disorder." (PMID 41479745, 2026). "In regression analyses, depression was associated with TNF-α (β = -0.133 to -0.152) and IL-6 (β = -0.171 to -0.207)." (PMID 41600880, 2026). "Another review examining the role of cytokines in adolescence found that IL-1β and TNF-α were associated with an increased risk of depression, and this relationship was influenced by neurodevelopment, hormonal changes, stress, and trauma." (PMID 39902492, 2025). "IFN-γ is associated with depression through two primary mechanisms: Similar to TNF-α, it can activate IDO, altering serotonin levels and producing neurotoxins." (PMID 39980978, 2025). "Tumor necrosis factor-α (TNF-α) also increased significantly in depressive patients (20.1 vs. 10.5 pg./mL, d = +1.22, p < 0.001), and contributed modestly to depression risk (OR = 1.03, 95% CI: 1.00–1.06)." (PMID 40823578, 2025). "While the first point rightly emphasizes their pro-inflammatory M1-like activation and the production of excess IL-1β and TNF-α, which increase neuronal hyperexcitability and seizure susceptibility, their involvement in depression is equally important." (PMID 40941042, 2025). "This process drives an imbalance between T helper 17 and regulatory T cells and elevates circulating levels of inflammatory cytokines such as IL-6, IL-1, and tumor necrosis factor, all of which are implicated in the pathogenesis of depression." (PMID 41409248, 2025). "Ischemic injury post-AMI triggers an inflammatory cascade, with elevated pro-inflammatory cytokines (IL-1β, IL-6, TNF-α, sICAM-1), which have been linked to depression and anxiety." (PMID 40142595, 2025). "Depression is associated with increased levels of proinflammatory cytokines, such as tumor necrosis factor-α (TNF-α), which also plays a key role in the pathophysiology of rheumatic disorders." (PMID 40837576, 2025). "Elevated levels of TNF-α and IL-6 have also been linked to depression, as they exacerbate and perpetuate neuroinflammatory processes, impairing brain function." (PMID 40141696, 2025). "Materials and Methods: In our study, we explored the association between TNF-α and IL-6, disease activity, and the degree of depression in patients with RA." (PMID 40699818, 2025). "This interplay between central and peripheral NF-κB/TNF-α signaling is considered a core mechanism underlying inflammation-induced depression-like behaviors." (PMID 40453075, 2025). "Estrogen also modulates inflammatory pathways, with low estrogen states associated with elevated pro-inflammatory cytokines (e.g., IL-6, TNF-α), which are implicated in depression." (PMID 40412096, 2025). "Studies have shown that depression is linked to elevated levels of pro-inflammatory cytokines such as IL-6, TNF-α, and CRP." (PMID 40697716, 2025). "A genome-wide association study revealed that genetic and epigenetic networks related to inflammation, such as polymorphisms in inflammatory mediators (CRP, tumor necrosis factor α, etc.), are closely associated with the severity of depression." (PMID 40365002, 2025). "The association between TNF-α and IL-6 and the Beck and Hamilton depression scales was analyzed in a group of 116 RA patients with depression." (PMID 40699818, 2025). "Participants who received the combined treatment showed significant improvements: ~25% cortisol reduction, ~3 kg weight loss, decreased IL-6 and TNF-α levels, and better scores on the Beck Depression Inventory-II and Perceived Stress Scale." (PMID 40649341, 2025).
depression (continued). "TNF-α is an additional important pro-inflammatory cytokine that contributes significantly to the inflammatory response and is linked to the aetiology of depression." (PMID 40574754, 2025). "The literature highlighted an association between sleep deprivation or depression and high levels of specific cytokines, (IL-1, IL-6 and TNF-α)." (PMID 39852224, 2025). "In contrast to IL-6, TNF-α and IL-1β levels were both associated with an increased odds of actually meeting criteria for clinical depression." (PMID 39902492, 2025). "A hallmark of depression is a heightened level of pro-inflammatory cytokines, including Tumor Necrosis Factor-α (TNF-α), Interleukin-6 (IL-6), and Interleukin-1β (IL-1β)." (PMID 41480347, 2025). "Inflammation, marked by elevated levels of cytokines such as interleukin-6 (IL-6) and tumor necrosis factor-alpha (TNF-α), has been directly associated with depression, suggesting an inflammatory component to the disorder." (PMID 39911326, 2025). "Inflammation plays a significant role in the overlap between sickness behavior and depression, as both are associated with elevated levels of pro-inflammatory cytokines, such as IL-1B, IL-6, and TNF-alpha." (PMID 40282388, 2025). "Individuals with depression often exhibit elevated levels of inflammatory markers including IL-1β, IL-6, TNF-α, and CRP, which are directly associated with acute cardiovascular events." (PMID 41179812, 2025). "This metabolic dysregulation further contributes to chronic inflammation, promoting the release of pro-inflammatory cytokines such as IL-6 and TNF-α, which have been implicated in both depression onset and severity." (PMID 40177085, 2025). "Research has shown that the excessive activation of pro-inflammatory cytokines, such as IL-1β, TNF-α, and IL-6, is closely associated with the pathogenesis of many central nervous system disorders, including depression." (PMID 40336842, 2025). "In terms of the outcome, this study primarily selected IL-1β, IL-6, and TNF-α as inflammatory biomarkers associated with depression." (PMID 41194929, 2025). "The regulation of the immune system, sleep, and circadian rhythms share common molecular mechanisms: IL-1β and TNF-α affect sleep and circadian rhythms to induce sleepiness, cognitive decline, depression, and fatigue, mimicking sleep loss symptoms." (PMID 40137863, 2025). "Although TNF-α also exhibited a positive association with depression, the effect was mild (p = 0.035), indicating a possible auxiliary role in the inflammatory cascade contributing to mood disturbances." (PMID 40823578, 2025). "According to network pharmacology results, IL-6, IL-1β, TNF-α, and IL-10 are closely associated with SD and depression." (PMID 40076470, 2025). "Depression exhibits close associations with elevated systemic inflammatory cytokines including interleukin-6 (IL-6), IL-1β, tumor necrosis factor-α (TNF-α), and C-reactive protein (CRP)." (PMID 40508038, 2025). "Elevated proinflammatory cytokines like IL‐6 and TNF‐α are associated with depression in cancer patients." (PMID 40387308, 2025). "Although effect sizes were small, higher levels of TNF-α, IL-1β, IL-6, and IL-8 were all linked to either more depressive symptoms and/or greater odds of meeting criteria for clinical depression." (PMID 39902492, 2025). "Variations in immune response genes like IL6 and TNF are linked to treatment-resistant epilepsy and depression, indicating common neuroinflammatory mechanisms." (PMID 40941042, 2025). "The purpose of this study was to examine associations between cytokines TNF-α, IL-1β, IL-6, and IL-8 and depression among a community-based sample of adolescents (13–19 years of age)." (PMID 39902492, 2025). "Studies have also shown that exercise reduces levels of pro-inflammatory factors (e.g., TNF-α and IL-6), which are strongly associated with suicidal tendencies and depression." (PMID 40584058, 2025).
depression (continued). "The results of subgroup analysis suggested that 8–12 weeks of exercise intervention is associated with a reduction in TNF-α levels in patients with depression." (PMID 41010394, 2025). "Elevated levels of pro-inflammatory cytokines such as IL-6 and TNF-α have been associated with depression, fatigue, and cognitive impairment, which are frequently reported in pSS." (PMID 40530052, 2025). "Inflammatory responses, characterized by elevated levels of proinflammatory cytokines such as interleukin‐6 (IL‐6) and tumor necrosis factor‐alpha (TNF‐α), have been implicated in the development of depression in cancer patients." (PMID 40387308, 2025). "Our model describes how TNFα concentration affects brain activity; specifically, in the cingulo-frontal circuit thought to underlie depression." (PMID 40352929, 2025). "Key gene–environment interactions, including those involving serotonin transporter (SLC6A4) and inflammatory genes (e.g., TNF-α, IL-6), have been implicated in depression." (PMID 40428308, 2025). "Emerging studies further highlight a close association between the development and progression of depression and the involvement of key proinflammatory cytokines IL-1β, TNF-α, and IL-6." (PMID 40710585, 2025). "In animals, pro-inflammatory cytokines induce a complex of behavioral and physiological changes, including changes in food intake and anhedonia, and TNF-α upregulation is associated with depressive disorders and depressive-like behavior in animal models." (PMID 41154178, 2025). "The levels of interleukin-1 beta (IL-1β), interleukin-6 (IL-6), and tumor necrosis factor (TNF) are associated with anxiety behavior and also with more severe depressive disorders." (PMID 40563433, 2025). "Its extracellular form acts as a pro-inflammatory cytokine that promotes the secretion of IL-6, TNF-α, and IL-1β, molecules that are closely linked to depressive disorder." (PMID 41375608, 2025). "Patients with depression exhibit similar changes associated with immune system activation, such as increased IL-6, TNF-α, and C-reactive protein levels." (PMID 38702637, 2024). "A meta-analysis demonstrated that interleukin-6 (IL-6), C-reactive protein (CRP), and tumor necrosis factor-α (TNF-α) are the inflammatory factors most closely associated with depression." (PMID 38877455, 2024). "Treatment-resistant depression cases in particular are associated with increased TNF concentrations." (PMID 39519725, 2024). "Increased cytokines that initiate the inflammatory cascade, such as interleukin-1 Beta (IL-1β), IL-6, and tumor necrosis factor (TNF), have been associated with severe depression linked to stress." (PMID 39335507, 2024). "Depression is known to be associated with neuroinflammation and with increased levels of C-reactive protein, interleukin-6 (IL-6) and tumor necrosis factor (TNF)-α." (PMID 39064764, 2024). "Secondly, a compelling association emerges between depression and an augmented inflammatory response, underscored by elevated levels of inflammatory mediators, notably cytokines like interleukin-6 and tumor necrosis factor-alpha, in affected individuals." (PMID 38805405, 2024). "Our results were consistent with several clinical studies that reported that levels of TNF-α were increased in peripheral and central neuronal systems of depressed patients, and was associated with the severity of depression." (PMID 38710713, 2024). "In this study, we aimed to more precisely assess the association between inflammation and depression by measuring inflammatory markers (IL-6, IL-1α, and TNF-α)." (PMID 39595067, 2024). "Specifically, cytokines such as IL-1β, IL-6, and TNF-α, associated with depression, can induce thermoregulatory abnormalities leading to fever and HFs14." (PMID 39019875, 2024). "On one hand, several studies relying on adult cross-sectional samples have shown positive associations between TNF-α and depression." (PMID 38586283, 2024).
depression (continued). "There is growing evidence that abnormal neuroinflammatory responses such as higher concentrations of pro-inflammatory cytokines such as TNFα and IL-1β in the brain promote susceptibility to psychiatric conditions like depression." (PMID 39682736, 2024). "Upon activation, microglial cells release inflammatory cytokines, such as IL‐6, TNF‐α, and IL‐1β, which are associated with the neuronal degeneration often observed in depression." (PMID 39554370, 2024). "The primary cytokines linked to depression consist of various indicators like Tumor Necrosis Factor α (TNFα), Interleukin (IL)-1β, IL-18, and Interferon (INF)-γ." (PMID 38731995, 2024). "Tumor necrosis factor-alpha (TNF-ά) promotes release of both IL-1β and IL-6 and is linked to chronic disease, including Alzheimer's disease, depression, cancer, chronic pain and multiples sclerosis." (PMID 39917641, 2024). "Elevated inflammatory factors, such as TNF-α and IL-6, are strongly associated with the development of depression." (PMID 39479195, 2024). "The elevated levels of certain cytokines are associated with inflammation in the brain, including interleukin-1 beta (IL-1β), interleukin-6 (IL-6), and tumor necrosis factor-alpha (TNF-α), which has been linked to the pathophysiology of depression." (PMID 39513898, 2024). "Lipocalin-2 (LCN2), a pro-inflammatory cytokine mediator, has been associated with depression and is often accompanied by elevated levels of IL-6 and TNF-α." (PMID 39273621, 2024). "Maternal infection, anxiety, or depression are associated with increased levels of pro-inflammatory cytokines, including TNF-α, IL-1β, and IL-6, not only in the maternal circulation but also in the fetal circulation and CNS." (PMID 38726788, 2024). "The most common cytokines which have been associated with depression are interleukin-1 (IL-1), IL-6, and tumor necrosis factor alpha (TNF-α)." (PMID 38673781, 2024). "Depression patients with high levels of tumor necrosis factor-α showed high risk of suicidal ideation and behavior than the low one (OR 2.16, 95% CI 1.00-4.65, P = 0.04)." (PMID 38459460, 2024). "Inflammatory factors released from adipose tissue, such as tumour necrosis factor-a (TNF-a) and interleukin-6 (IL-6), can travel through the bloodstream to the brain and cause depression." (PMID 39346588, 2024). "Both animal models and clinical studies demonstrate an increased inflammatory milieu associated with depression, including increased levels of interleukin-1beta (IL-1b), IL-6, tumor necrosis factor-alpha (TNFa), and interferon-gamma (IFN-g)." (PMID 39297528, 2024). "Since the early 1990s, studies have associated depressive disorders with altered levels of circulating inflammatory markers, such as interleukin (IL)-6 and tumor necrosis factor (TNF)." (PMID 35796659, 2024). "Several studies have reported that inflammation in the brain and the associated over-release of pro-inflammatory cytokines TNF-α, IL-6, or IL-1β can lead to a loss of hippocampal neurogenesis, promoting depression-like behaviors." (PMID 37238920, 2023). "Cytokines such as IL-6 and TNF-α are known to be involved in IFN-α-induced depression and high levels of these cytokines is associated with increased risk of major depressive disorder." (PMID 36911685, 2023). "Increased inflammatory cytokines in the brain and in serum, such as CRP, and soluble cell-adhesion molecules IL-6, IL-1β, TNF-α and NF-κB, would be involved in the susceptibility to depression in stressed obese mice." (PMID 37836393, 2023). "Higher TNF-α levels were associated with post-stroke depression at 2 weeks in the presence of the −850T allele." (PMID 37510364, 2023). "Studies should also assess the levels of other inflammatory markers such as IL-6, TNF-α and their association with postoperative depression." (PMID 37928924, 2023).